SEPTIN3 (septin 3)
Description:
Filament-forming cytoskeletal GTPase (By similarity). May play a role in cytokinesis (Potential).
Synonyms: SEP3; SEPT3; bK250D10.3
Tractability: Small molecule: a structure with a bound ligand is known. Antibody: the Human Protein Atlas places it where antibodies can reach. PROTAC: ubiquitination databases record sites on it.
Safety:
Unwanted effects reported when the protein is acted on. In parentheses: how it was acted on, where the effect was seen, and who reports it.
adverse events (source: ClinPGx)
Gene: Protein-coding gene on chromosome 22 (41,969,443 to 41,998,221, forward strand). Ensembl gene ENSG00000100167.
Subcellular location: Cytoplasm; Cytoplasm, cytoskeleton; Synapse
Subcellular location (Human Protein Atlas): Actin filaments; Plasma membrane; Nucleoplasm; Primary cilium
Gene Ontology:
Molecular function: identical protein binding; protein binding; GTPase activity; molecular adaptor activity; GTP binding
Biological process: cytoskeleton organization; cytoskeleton-dependent cytokinesis; intracellular protein localization
Cellular component: cell division site; microtubule cytoskeleton; presynapse; septin complex; septin ring; cytoplasm; cytoskeleton; synapse
Genetic constraint (gnomAD): Loss-of-function variants: 13 observed, 35.15 expected, observed/expected ratio (o/e) 0.37, 90% interval 0.24 to 0.59. The upper end of that interval is the gene's LOEUF score, 0.59, which puts it in group 2 of 6, group 1 being the genes least tolerant of losing a copy. Missense variants: 276 observed, 446.69 expected, observed/expected ratio (o/e) 0.62, 90% interval 0.56 to 0.68. Synonymous variants: 136 observed, 163.25 expected, observed/expected ratio (o/e) 0.83, 90% interval 0.72 to 0.96.
Homologues: Orthologues: macaque SEPTIN3 (95% identical), pig SEPTIN3 (76% identical), dog SEPTIN3 (74% identical), rat Septin3 (68% identical), mouse Septin3 (66% identical), tropical clawed frog septin3 (42% identical), chimpanzee SEPTIN3 (42% identical), guinea pig Septin3 (41% identical), zebrafish septin3 (33% identical), Drosophila melanogaster Septin2 (16% identical), Caenorhabditis elegans unc-61 (14% identical). Paralogues in human: SEPTIN9 (30% identical), SEPTIN12 (22% identical), SEPTIN5 (18% identical), SEPTIN7 (18% identical), SEPTIN2 (18% identical), SEPTIN1 (17% identical), SEPTIN11 (16% identical), SEPTIN10 (16% identical), SEPTIN8 (16% identical), SEPTIN6 (16% identical), SEPTIN14 (15% identical), TMEM250 (3% identical).
Diseases named in the same sentence as SEPTIN3 in open-access papers:
SEPTIN3 is named in the same sentence as 27 diseases in open-access papers, as found by Europe PMC text mining. Sharing a sentence is not in itself a finding about the gene and the disease. The quoted sentences say what the papers report.
melanoma (2 papers, 2020 to 2023). A malignant, usually aggressive tumor composed of atypical, neoplastic melanocytes. "All three patients analyzed had cancer (2 × melanoma, with a lymph node metastasis in one of them; 1 × small cell lung cancer with lymph node metastases), suggesting that septin-3 IgG-associated autoimmune cerebellar ataxia may be a novel paraneoplastic neurological syndrome (PNS)." (PMID 36997937, 2023). "The analysis of paraffin-embedded tumor sections from patient 1 using conventional IHC with an anti-septin-3-specific commercial antibody, revealed areas with high expression of septin-3 both in the melanoma and in the lymph node metastasis." (PMID 36997937, 2023).
squamous cell carcinoma (2 papers, 2025). A carcinoma arising from squamous epithelial cells. "Tier 2 proteins, supported by transcriptomic evidence but not sensitivity analyses, included AGRN, ITGB2, SEPTIN3 (adenocarcinoma) and DPP10 (squamous cell carcinoma)." (PMID 41340014, 2025).
autism (1 paper, 2025). Persistent deficits in social interaction and communication and interaction as well as a markedly restricted repertoire of activity and interest as well as repetitive patterns of behavior. "Two members of the GTP-binding cytoskeletal septin protein family, namely septin 3 and 6 were reduced significantly in children with autism (septin 3: log2 FC = -0.2572, FDR adj." (PMID 40779003, 2025).
Autoimmunity (1 paper, 2023). The occurrence of an immune reaction against the organism's own cells or tissues. "Thus we suggest inclusion of the septin-3/5/6/7/11 complex in neuronal autoimmunity routine testing." (PMID 36997937, 2023). "While the tissue IIFA neutralization experiments indicate that the tissue pattern was caused by anti-septin-3 autoantibodies, it cannot be ruled out that the patient’s clinical symptoms were in part also related to autoimmunity to GABAB receptor and/or GAD65." (PMID 36997937, 2023). "Altogether, the different clinical phenotypes reported in patients with anti-septin-3, anti-septin-5 or anti-septin-7 autoimmunity so far suggest that these autoantibodies may be markers for different clinical presentations." (PMID 36997937, 2023).
cerebellar ataxia (1 paper, 2023). A neurological syndrome characterized by clumsy and uncoordinated movement of the limbs, trunk, and cranial muscles. "Septin-3 antibodies form part of a broader spectrum of novel autoantibodies associated with cerebellar ataxia that have been discovered over the past two decades, some of which are of paraneoplastic origin." (PMID 36997937, 2023). "Here, we report on septin-3 as a novel autoimmune target antigen in patients with paraneoplastic cerebellar ataxia." (PMID 36997937, 2023). "Here, we report on newly identified autoantibodies against septin-3 in patients with paraneoplastic cerebellar ataxia." (PMID 36997937, 2023).
colon cancer (1 paper, 2023). "Accordingly, both technologies reported the overexpression of STIM1, MBP, SEPTIN9, and SEPTIN10 and the downregulation of CRACR2A, ORMDL3, SARAF, SEPTIN3, and SEPTIN6 in colon cancer cells." (PMID 36900391, 2023).
colorectal cancer (1 paper, 2023). A primary or metastatic malignant neoplasm that affects the colon or rectum. "The SEPTIN3 protein has previously been shown to be ectopically expressed in TB, colorectal cancer, and urologic cancers such that it can be leveraged as a valuable diagnostic biomarker." (PMID 37205113, 2023).
endometrial cancer (1 paper, 2020). Primary or metastatic malignant neoplasm involving the endometrium (mucous membrane that lines the endometrial cavity). "Analyses of The Cancer Genome Atlas (TCGA) show that both septin-2 and septin-3 overexpression correlate with increased mortality in endometrial cancer." (PMID 32094384, 2020).
intestinal tumors (1 paper, 2023). "Mutations of septin-3 have most frequently been observed in lung, skin and intestinal tumors." (PMID 36997937, 2023).
lung adenocarcinoma (1 paper, 2025). A carcinoma that arises from the lung and is characterized by the presence of malignant glandular epithelial cells. "For the significant proteins identified in the observational analyses, Agrin (AGRN), CD5 antigen‐like (CD5L), glucosamine‐6‐phosphate isomerase 1 (GNPDA1), integrin beta‐2 (ITGB2) and neuronal‐specific septin‐3 (SEPTIN3) remained associated with lung adenocarcinoma in the two‐sample MR analyses." (PMID 41340014, 2025). "Although there is no direct evidence linking SEPTIN3 protein to lung adenocarcinoma risk, previous studies have shown that high SEPTIN3 expression promotes the progression of triple‐negative breast cancer." (PMID 41340014, 2025).
multiple sclerosis (1 paper, 2023). A progressive autoimmune disorder affecting the central nervous system resulting in demyelination. "Furthermore, 59 sera of patients with multiple sclerosis and 50 sera of patients positive for different anti-neuronal autoantibodies (10 × anti-Yo, 10 × anti-Ri, 10 × anti-GAD65, 10 × anti-ITPR1, 10 × Sez6l2) were analyzed using RC-IIFA with HEK293-septin-3/5/6/7/11 complex cells as controls." (PMID 36997937, 2023).
Parkinson disease (1 paper, 2012). A progressive degenerative disorder of the central nervous system characterized by loss of dopamine producing neurons in the substantia nigra and the presence of Lewy bodies in the substantia nigra and locus coeruleus. "Septin 3 and 5 are both down-regulated in pR5, with Septin 5 accumulating in Parkinson's disease (PD) brain." (PMID 22558197, 2012).
tumor (6 papers, 2021 to 2025). "Expression of septin-3 was demonstrated in resected tumor tissue available from one patient." (PMID 36997937, 2023). "Finally, tumor tissue sections were analyzed immunohistochemically for septin-3 expression." (PMID 36997937, 2023). "The hub node in PRAD and adjacent normal prostate tissues was shown in, RIMKLA, TPD52, and SEPTIN3 were highly expressed in PRAD, while other genes were low-expressed in tumor tissues in." (PMID 40341647, 2025). "Indeed, septin-3, which is usually absent outside the CNS, was ectopically and strongly expressed in two tumor samples from one of our patients, corroborating this notion." (PMID 36997937, 2023). "However, as no tumor material was available of patient 2 and 3, we could not investigate septin-3 expression in these cases." (PMID 36997937, 2023).
SEPTIN3 also shares sentences with these, for which no sentence is quoted: cancer (3 papers); Alzheimer disease (2); infection (2); lung carcinoma (2); adenocarcinoma (1); Cognitive impairment (1); epilepsy (1); glioma (1); lymph node metastases (1); mental disorder (1); paraneoplastic neurological syndrome (1); schizophrenia (1); small cell carcinoma (1); small cell lung carcinoma (1).